TOMM40 (translocase of outer mitochondrial membrane 40)
Diseases named in the same sentence as TOMM40 in open-access papers (continued):
Sharing a sentence is not in itself a finding about the gene and the disease.
steatosis (2 papers, 2021 to 2024). Increased lipid within the cytoplasm of cells. "This caveat was showcased by the variant rs2075650 residing in an intron of TOMM40, which was found to be associated with steatosis." (PMID 34950105, 2021).
cardiac arrhythmia (1 paper, 2021). Any disturbances of the normal rhythmic beating of the heart or MYOCARDIAL CONTRACTION. "Additionally, experimental evidence showed that homozygous deletion of TOMM40 in mammals was lethal, and heterozygous TOMM40 knockdown mice were found to have cardiac arrhythmia that deteriorated with age." (PMID 34651031, 2021).
cardiac conduction disease (1 paper, 2024). "According to our knowledge, this is the first observational clinical study that attempted to investigate the TOMM40 genetic variants in cardiovascular and cardiac conduction disorders." (PMID 38892888, 2024). "On the other hand, we showed an association between TOMM40 Xg polymorphism and higher LBBB incidence, suggesting a role of mitochondria machinery in cardiac conduction diseases." (PMID 38892888, 2024).
cholangiocarcinoma (1 paper, 2025). A carcinoma that arises from the intrahepatic biliary tree (intrahepatic cholangiocarcinoma) or from the junction, or adjacent to the junction, of the right and left hepatic ducts (hilar cholangiocarcinoma). "Based on the UALCAN analysis, we found that NKILA, MTX1, and TOMM40 were highly expressed in cholangiocarcinoma." (PMID 41498025, 2025). "Furthermore, GEPIA analysis unveiled upregulation of TOMM40 in cholangiocarcinoma." (PMID 41498025, 2025).
cognitive diseases (1 paper, 2022). "Here we provide evidence that elevated mitochondrial TOM levels trigger cell death in an in vivo Drosophila model, illuminating a possible connection to TOMM40-related neurodegeneration and cognitive diseases associated with ageing." (PMID 36517509, 2022).
depression (1 paper, 2024). "Polymorphisms in mitochondrial genes such as TOMM40, ATP6V1B2, and MOA are correlated to depression in humans." (PMID 38800537, 2024).
glioma (1 paper, 2020). A benign or malignant brain and spinal cord tumor that arises from glial cells (astrocytes, oligodendrocytes, ependymal cells). "We previously reported significantly higher TOMM40 expression in EVs from GBM neurosurgical aspirates compared to GII-III glioma." (PMID 32635403, 2020). "Increased levels of TOMM40 in GBM/GIV plasma-EVs relative to GII-GIII gliomas, as well as non-glioma and healthy controls, may be a useful distinguishing circulating biomarker for GBM and should be further explored." (PMID 32635403, 2020).
Hepatic steatosis (1 paper, 2024). Steatosis is a term used to denote lipid accumulation within hepatocytes. "Although Tomm40 KD in both sexes induced hepatic steatosis, the intracellular mechanisms were found to be different." (PMID 39489289, 2024). "In addition to promoting hepatic steatosis, in vivo KD of Tomm40 in mice resulted in significant reductions in plasma lipid and lipoprotein levels that were greater in males." (PMID 39489289, 2024). "•Hepatic TOMM40 knockdown increases triglyceride content, lipid droplets, and hepatic steatosis." (PMID 39489289, 2024). "Consequently, Tomm40 KD mice developed hepatic steatosis based on histological (H&E and ORO) assessments and quantification of plasma AST and ALT levels." (PMID 39489289, 2024). "Furthermore, mechanisms other than suppression of the seipin pathway could be responsible for promoting LD accumulation and hepatic steatosis with Tomm40 KD in females, and it is possible that these mechanisms are also operative in males." (PMID 39489289, 2024).
hepatoma (1 paper, 2024). "Consistent with prior studies in HeLa cells and C. Elegans, knockdown (KD) of TOMM40/TOMM40 in human hepatoma HepG2 cells resulted in reduction of basal and maximal respiration and ATP production as well as proton leak compared to non-targeting control (NTC)." (PMID 39489289, 2024). "TOMM40 was knocked down by siRNA in human hepatoma HepG2 cells, and effects on mitochondrial function, lipid phenotypes, and crosstalk between mitochondria, ER, and lipid droplets were examined." (PMID 39489289, 2024).
Hypercholesterolemia (1 paper, 2022). An increased concentration of cholesterol in the blood. "The results of subgroup analyses indicated that the TOMM40 gene was associated with hypercholesterolemia in peri- and postmenopausal women." (PMID 36233190, 2022).
Hypertension (1 paper, 2024). The presence of chronic increased pressure in the systemic arterial system. "We also identified Translocase Of Outer Mitochondrial Membrane 40 (TOMM40) variants associated with CAD; Solute carrier family 22 member 2 (SLC22A2) variants associated with CAD and CVD; and HLA-DQA1 variants associated with hypertension." (PMID 39258111, 2024). "TOMM40, one of the genes associated with CAD but not with CVD or the blood pressure related phenotypes (hypertension, SBP and DBP), was common for all the serum lipids, along with SLC22A2, which was common for CVD and all serum lipids." (PMID 39258111, 2024).
leukemia (1 paper, 2024). A malignant (clonal) hematologic disorder, involving hematopoietic stem cells and characterized by the presence of primitive or atypical myeloid or lymphoid cells in the bone marrow and the blood. "Recently, a novel receptor on NK lymphocytes was reported to bind to TOMM40 on K562 leukemia cells, thereby initiating cytolysis, which may be related to the promotion of tumor cell growth." (PMID 38285218, 2024).
melanoma (1 paper, 2020). A malignant, usually aggressive tumor composed of atypical, neoplastic melanocytes. "High TOMM40 levels are associated with a super-invasive subtype of melanoma, with BRCA1/2 expression and mutations and is a histological feature for the squamous subtype of non-small cell lung cancer." (PMID 32635403, 2020).
memory impairment (1 paper, 2015). "Two genes are consistently associated with all seven memory scores: neuron navigator 2 (NAV2) and Translocase Of Outer Mitochondrial Membrane 40 Homolog (TOMM40), where TOMM40 is proximal to APOE and has been reported to be associated with the memory impairment." (PMID 25859259, 2015).
neovascular age-related macular degeneration (1 paper, 2013). "We aimed to examine the associations between the TOMM40 rs2075650 polymorphism and neovascular age-related macular degeneration (nAMD) and polypoidal choroidal vasculopathy (PCV) in a Chinese population." (PMID 24146538, 2013).
neuroblastoma (1 paper, 2020). Neuroblastoma (NB) is the most common solid, extracranial childhood tumor. "We have preliminary evidence that it also coactivates the transcription of TOMM40 in neuroblastoma cells." (PMID 32472747, 2020).
Onset (1 paper, 2022). The age group in which disease manifestations appear. "TOMM40 has been reported to be associated with late-onset AD, where the mitochondrial dysfunction is believed to be the underlying cause." (PMID 35839250, 2022).
schizophrenia (1 paper, 2024). A major psychotic disorder characterized by abnormalities in the perception or expression of reality. "Finally, we identified CSNK2B, TOMM40, MAP1LC3B, MFN1, CSNK2A2, PGAM5 and ATG12 as the diagnostic genes for schizophrenia." (PMID 39355378, 2024).
Senile plaques (1 paper, 2025). Senile plaques are extracellular deposits of amyloid in the gray matter of the brain. "Mitochondrial dysfunction is observed around senile plaques, notable lesions constituting aggregated Aβ and tau protein; TOMM40 is implicated in the inflow of proteins and Aβ into mitochondria." (PMID 39975850, 2025).
ulcerative colitis (1 paper, 2021). An inflammatory bowel disease involving the mucosal surface of the large intestine and rectum. "Curiously, some of the genes highlighted here, such as TOMM40 and TUBB6, were associated not only with neurodegenerative diseases, like Alzheimer’s, but also with ulcerative colitis." (PMID 33936067, 2021).
tumor (12 papers, 2018 to 2025). "Our analysis revealed a significant correlation between TOMM40 expression and the clinical features of patients, as well as its impact on tumor-associated overall survival (OS), disease-specific survival (DSS) and progression-free survival (PFS)." (PMID 39060752, 2024). "Intriguingly, the TCM score showed a strong association with TOMM40, which we experimentally validated as an oncogene promoting tumour proliferation, invasion and migration." (PMID 39054572, 2024). "Clinical sample validation showed that MTX1 and TOMM40 expressions were higher in tumor tissues than adjacent tissues (p < 0.01)." (PMID 41498025, 2025). "In most cancers, TOMM40 and FH were upregulated in the tumor group, suggesting that TOMM40 and FH play an important role in malignant proliferation and invasion." (PMID 38285218, 2024). "In addition, in most cancers, TOMM40 and FH expression differed significantly between tumor tissue and normal paracancerous tissue." (PMID 38285218, 2024). "We speculate that upregulation of TOMM40 may improve the prognosis of patients by promoting tumor immunity." (PMID 34368262, 2021). "Further analysis of the model genes within TCM across pan‐cancer settings revealed that TOMM40, NNT5DC2, NNME, KPNA2, FFOXM1 and AP2S1 were predominantly overexpressed in tumour tissues, while TYRP were highly expressed in normal tissues." (PMID 39054572, 2024).
cancer (9 papers, 2013 to 2025). A tumor composed of atypical neoplastic, often pleomorphic cells that invade other tissues. "Based on CIBERSORT analysis, there was an association between immune cell infiltration and TOMM40 expression in several types of cancer." (PMID 39060752, 2024). "The analysis of TOMM40 in PCOS revealed that its metabolic pathways are associated with cancer-related pathways, such as the Wnt signaling pathway, HIF-1 signaling pathway, and central carbon metabolism in cancer." (PMID 39060752, 2024). "Furthermore, numerous research has indicated that TOMM40 functions as a cancer-causing gene in malignancies and enhances the advancement of tumors." (PMID 39060752, 2024). "Given the strong correlation between PCOS, inflammation, immunity, and endothelial activation, we were motivated to utilize bioinformatics pan-cancer database analysis techniques to investigate the involvement of TOMM40, a gene associated with PCOS, in various types of cancer." (PMID 39060752, 2024). "According to the study findings, it is hypothesized that TOMM40 associated with PCOS could potentially serve as a prognostic indicator for various types of cancer." (PMID 39060752, 2024). "The analysis of the operating system showed that the correlation between TOMM40 expression and OS was significant in four types of cancer, namely LGG, LIHC, LUAD, and SKCM, acting as protective factors." (PMID 39060752, 2024). "In various types of cancers, the expression level of TOMM40 showed a positive correlation with CD8 T cells, T cells and Endothelial cells." (PMID 39060752, 2024). "To further analyze the important roles of TOMM40 and FH in other malignancies, we performed a pan-cancer analysis of TOMM40 and FH." (PMID 38285218, 2024). "The analysis conducted in DSS showed a significant association between TOMM40 expression and DSS in 5 types of cancer (ACC, KIRP, LGG, LUAD, and SKCM), where TOMM40 expression acted as a protective factor." (PMID 39060752, 2024). "Having an in-depth understanding of the role of immunity and the development of cancer in human would advance our understanding of TOMM40 as a factor in follicle development and PCOS." (PMID 39060752, 2024). "Of note, one OCRG shared by all five cancer groups was translocase of outer MT membrane 40 (TOMM40)." (PMID 34368262, 2021). "Our analysis unveiled a significant oncogenic expression of TOMM40 across various cancer types." (PMID 39060752, 2024). "We also performed the co-expression analysis of TOMM40 and FH with immune-related cells, and TOMM40 and FH could affect immune cell infiltration in pan-cancer." (PMID 38285218, 2024). "TOMM40 and FH were associated with TMB and MSI in a range of cancers." (PMID 38285218, 2024). "Numerous research studies have indicated that the TOMM40 gene might play a role in increasing the likelihood of developing cancer." (PMID 39060752, 2024). "We also found that TOMM40 was upregulated in 14 out of 33 types of cancers (42.4%)." (PMID 34368262, 2021). "It remains unknown whether this innate immune function of TOMM70 is correlated with the better prognosis of cancers upregulating TOMM40 complexes." (PMID 34368262, 2021). "We further determined whether increased expressions of TOMM40 and 10 interaction proteins in cancers lead to better prognosis by analyzing the overall survival map of hazard ratio (HR) and disease-free survival map [relapse-free survival (RFS)] of TOMM40 and 10 interaction proteins." (PMID 34368262, 2021). "Through the application of bioinformatics and molecular biology techniques, this study has identified a significant association between translocase of outer mitochondrial membrane 40 (TOMM40) and both PCOS and pan-cancers." (PMID 39060752, 2024). "Based on the bioinformatics discoveries of PCOS and pan-cancer, our conclusion is that TOMM40 could potentially function as a potential -biomarker for the prediction and diagnosis of both PCOS and pan-cancer." (PMID 39060752, 2024).
cancer (continued). "These pieces of evidence indicate that TOMM40 significantly contributes to both PCOS and cancer." (PMID 39060752, 2024). "A study reported that TOMM40 pseudogene transcripts are expressed across different tissue types in both cancer and non-cancer cells." (PMID 35964003, 2022). "For the inferred perturbed miR-125 regulatory networks, there are only three common targets (CDK16, TOMM40 and KIAA1522), which suggests that miR-125 may regulate different pathways in the two types of cancers." (PMID 24278370, 2013). "Therefore, TOMM40 can be regarded as a promising biomarker for diagnosing both PCOS and pan-cancer." (PMID 39060752, 2024).
neurodegenerative disease (8 papers, 2018 to 2025). A disorder of the central nervous system characterized by gradual and progressive loss of neural tissue and neurologic function. "This included two known proteins associated with MERCS, MFN2 and TOMM40, as well as neurodegenerative disease-associated genes such as WIPI2, CLASRP, BAG6, SOD1 and FUS which increase MERCS and MTCH2 and PARL which decrease MERCS." (PMID 38467609, 2024). "The role of TOMM40 in mitochondrial dysfunction is further supported by existing literature where a reduction in protein expression levels has been found in neurodegenerative diseases." (PMID 33804213, 2021). "Investigating the TOMM40 role in protein import and lipid metabolism may help to better understand age-related neurodegenerative diseases and assess the necessity of therapeutic interventions." (PMID 41465142, 2025).
infection (6 papers, 2007 to 2025). The state of being infected such as from the introduction of a foreign agent such as serum, vaccine, antigenic substance or organism. "And protein levels showed that silencing did knock downTOMM22 and TOMM40 expression was only reduced a little bit after infection." (PMID 41433368, 2025).
neurological disease (2 papers, 2015 to 2021). "Besides that, in this LD block, several variants act as eQTLs/sQTLs in the brain and whole blood, altering the expression of many genes already related to LOAD or other neurological diseases in human or animal studies, such as CELF1 itself, MADD, MYBPC3, NR1H3, NUP160, SPI1, and TOMM40." (PMID 34291080, 2021).
TOMM40 also shares sentences with these, for which no sentence is quoted: angina pectoris (2 papers); Parkinsonism (2); amyloid (1); asthma (1); atherosclerotic heart disease (1); cardiac conduction disorders (1); cardiac diseases (1); cardiomyopathy (1); cardiovascular disease (1); colorectal cancer (1); cyst (1); diabetes mellitus type 2 (1); galactosemia (1); Hashimoto thyroiditis (1); Huntington disease (1); inclusion body myositis (1); Insulin resistance (1); legionellosis (1); Lewy body dementia (1); Listeria infection (1); liver cancer (1); liver disease (1); mitochondrial protein import disorder (1); multiple sclerosis (1); myocardial infarction (1); myopathy (1); nasopharyngeal carcinoma (1); nasopharyngitis (1); neurodevelopmental disorder (1); non-small cell lung carcinoma (1).
A further 10 diseases each share a sentence with TOMM40 in 1 paper.